TNF (tumor necrosis factor)
Diseases named in the same sentence as TNF in open-access papers (continued):
Sharing a sentence is not in itself a finding about the gene and the disease.
rheumatoid arthritis (continued). "Among this list, the mAb adalimumab (ADA), a tumor necrosis factor-alpha (TNF-α) inhibitor used to treat rheumatoid arthritis and related disorders, was the most profitable product each year, generating global sales of approximately USD 62.6 billion between 2014 and 2017." (PMID 36013214, 2022). "The aim of our study is to systematically elucidate the biological processes underlying non-response to anti-TNF therapy in rheumatoid arthritis using the gene ontologies of previously published predictive biomarkers." (PMID 36009355, 2022). "While existing therapeutic interventions do indicate some pathway biases in disease pathogenesis, such as TNF inhibitors in rheumatoid arthritis or IL17 inhibitors in psoriasis, our data demonstrate that orally administered EDP1867 is effective in murine models of Th1, Th2 and Th17 inflammation." (PMID 35185874, 2022). "While rheumatoid arthritis patients and tumor necrosis factor transgenic (TNF-Tg) mice with inflammatory-erosive arthritis display lymphatic drainage deficits, the mechanisms responsible remain unknown." (PMID 35882971, 2022). "Moreover, a feedback loop of TNF-α-induced XBP1 in rheumatoid arthritis synoviocytes has been observed." (PMID 36421428, 2022). "KEGG pathway enrichment results showed that upregulated DEGs are enriched in “Rheumatoid arthritis”, “IL−17 signaling pathway”, “Cytokine−cytokine receptor interaction”, “Wnt signaling pathway”, “Neuroactive ligand−receptor interaction”, and “TNF signaling pathway”." (PMID 36238159, 2022). "The results of our study help to elucidate the mechanisms underlying response and non-response to anti-TNF therapy in rheumatoid arthritis." (PMID 36009355, 2022). "Both IL-6 and TNF-α play critical roles in the immunopathogenesis of rheumatoid arthritis." (PMID 35009001, 2022). "Therefore, agents that block the action of TNF have the ability to treat a range of inflammatory diseases, including rheumatoid arthritis, ankylosing spondylitis, inflammatory bowel disease, and psoriasis." (PMID 36554354, 2022). "Adalimumab is a TNF-α inhibitor used in clinical practice in the treatment of many diseases such as psoriasis, psoriatic arthritis, rheumatoid arthritis, ankylosing spondylitis, inflammatory bowel diseases (Crohn’s disease and ulcerative colitis), and juvenile idiopathic arthritis." (PMID 36945982, 2022). "It has been reported that in rheumatoid arthritis, the blood levels of IL-6 and TNF-α increase." (PMID 36601050, 2022). "Tumor necrosis factor-α (TNF-α) is an important pro-inflammatory cytokine, and its elevated level correlates with a broad range of inflammatory diseases such as rheumatoid arthritis (RA), psoriasis, and Crohn’s disease." (PMID 35402370, 2022). "The results of our gene ontology analysis help elucidate the biological processes underlying non-response to anti-TNF therapy in rheumatoid arthritis and encourage further study of the highlighted processes." (PMID 36009355, 2022). "The top 10 KEGG pathways were: TNF signaling pathway, IL-17 signaling pathway, rheumatoid arthritis, C-type lectin receptor signaling pathway, osteoclast differentiation, leishmaniasis, coronavirus disease, asthma, Chagas disease, malaria, and Toll like receptor signaling pathway." (PMID 36380355, 2022). "Since FLS (fibroblast-like synoviocytes) play an important role in the pathogenesis of rheumatoid arthritis (RA), we investigated whether TNFα response in FLS is influenced by the matrix in which FLS were cultured." (PMID 36045678, 2022). "We applied a combined analysis of single-cell (sc) transcriptomes and epigenomes (scRNA-seq and scATAC-seq) to SFs derived from naïve and hTNFtg mice (mice that overexpress human TNF, a murine model for rheumatoid arthritis), by employing the Seurat and ArchR packages." (PMID 35879783, 2022).
rheumatoid arthritis (continued). "Different studies have shown the impact of TNF inhibitors on weight gain with variable and heterogeneous data; however, till now, we have no clear answer for the effect of these medications on seropositive patients with rheumatoid arthritis." (PMID 35784983, 2022). "In addition, treatment of synovial fibroblasts derived from rheumatoid arthritis patients with TQ (1–5 μM) for 24 h decreased ICAM-1 gene expression despite pre-stimulation with TNF-α." (PMID 35723378, 2022). "In addition, VEGF has proinflammatory and antiapoptotic roles in the pathogenesis of rheumatoid arthritis, and induces tumor necrosis factor-α and interleukin 6 from mononuclear cells in the synovial fluid of patients with rheumatoid arthritis." (PMID 36551311, 2022). "Similarly to FeNPs, they induced a significant increase in the TNFα concentrations, which is probably responsible for promoting non-specific inflammatory response accelerating in turn the progression of rheumatoid arthritis." (PMID 35900599, 2022). "Besides cytokines that are mainly produced by monocytes/macrophages, such as TNF-α and IL-6, T lymphocytes were reported to participate in the production of some inflammatory cytokines in rheumatoid arthritis." (PMID 35335895, 2022). "TNF-α is one of the cytokines which has significant pro-inflammatory role in rheumatoid arthritis." (PMID 35422870, 2022). "A systematic review and meta-analysis evaluating the relationship between anti-tumor necrosis factor (anti-TNF) therapy and cardiovascular events in patients with rheumatoid arthritis showed that cardiovascular events were related with a lower risk when anti-TNF medication was used." (PMID 36703734, 2022). "A vast spectrum of functions and activities in host defense and the initiation and maintenance of inflammation was demonstrated and “TNF blockade” is commonly used in anti-inflammatory therapies for chronic inflammatory diseases such as rheumatoid arthritis (RA)." (PMID 36358688, 2022). "Tumor necrosis factor-alpha (TNF-α)therapy, in conditions such as rheumatoid arthritis, may also be associated withimproved outcomes in CVD." (PMID 39076638, 2022). "In rheumatoid arthritis patients, chronic exposure of total T cells to TNFα impairs cell-mediated immune responses via CD28 downregulation whereas memory CD4+CD45RO+ T cells acquire a stronger Th17 pathogenic profile compared to cells from healthy donors under Th17-polarizing conditions." (PMID 35216459, 2022). "One of the factors that contribute to rheumatoid arthritis is tumor necrosis factor (TNF)-α." (PMID 35953935, 2022). "Moreover, proinflammatory cytokine IL-6 is secreted upon activation of Notch2 by tumor necrosis factor-α (TNF-α) in rheumatoid arthritis models." (PMID 35492721, 2022). "We examined whether genetic ablation of DC-STAMP attenuates synovitis and bone erosion in TNF transgenic (Tg) and K/BxN serum-induced murine rheumatoid arthritis." (PMID 36420272, 2022). "Additionally, it should be noted that people with immune-mediated inflammatory diseases; such as, inflammatory bowel disease (IBD) or rheumatoid arthritis and are under anti-TNF therapy, usually show decreased odds of hospitalization or intensive care." (PMID 36574379, 2022). "The study went further to demonstrate that inflammatory cytokines such as interleukin 1 (IL-1), interleukin 17 (IL-17) and tumor necrosis factor alpha (TNF-α) expressed during rheumatoid arthritis leads to increases in myostatin expression which in turns enhances osteoclast differentiation." (PMID 36151243, 2022). "RNA biomarker subsets revealed several enriched GO terms that were not previously directly associated with anti-TNF therapy response in rheumatoid arthritis." (PMID 36009355, 2022).
rheumatoid arthritis (continued). "KEGG pathway analysis showed that these DEGs were mainly involved in the IL-17 signaling pathway, inflammatory bowel disease, rheumatoid arthritis, allograft rejection, T cell receptor signaling pathway, cytokine-cytokine receptor interaction, and TNF signaling pathway." (PMID 36051483, 2022). "TNFα is perhaps one of the best-known inflammatory mediators as TNFα blocking agents show efficacy in a range of inflammatory diseases, including but not limited to, rheumatoid arthritis and psoriasis." (PMID 36293102, 2022). "S100A4 is a potent trigger of inflammatory molecules, such as interleukin (IL)-1, IL-6, tumor necrosis factor (TNF)-a, and matrix metalloproteinases, which are involved in autoimmune disease developments, such as allergies, rheumatoid arthritis, systemic sclerosis, and psoriasis, etc.." (PMID 36361563, 2022). "For example, anti-TNFα is an effective drug for rheumatoid arthritis and Crohn’s diseases." (PMID 36668761, 2022). "In line with published literature, our analysis shows that the widespread adoption of TNF-alpha inhibitor biosimilars has been limited by the indication of these products to treat chronic conditions (e.g., rheumatoid arthritis, ankylosing spondylitis, Crohn’s disease, ulcerative colitis, etc.)." (PMID 36703896, 2022). "Videos on rheumatoid arthritis, dialysis, and self-injection of anti-tumor necrosis factor agents showed similar results to those of our study (63.6%, high-quality videos; 50%, accurate videos) and that up to 50% of these YouTube videos included useful medical information and good quality." (PMID 36291450, 2022). "The top 5 enriched pathways according to the adjusted p value were rheumatoid arthritis (hsa05323), the TNF signaling pathway (hsa04668), the IL-17 signaling pathway (hsa04657), the AGE-RAGE signaling pathway in diabetic complications (hsa04933), fluid shear stress and atherosclerosis (hsa05418)." (PMID 36422594, 2022). "Indeed, clinical trials showed that GM-CSF-targeted therapy was efficacious in patients with rheumatoid arthritis who were unresponsive to anti-TNF-α therapy." (PMID 34980171, 2022). "KEGG enrichment analysis results showed that the 172 common DEGs were mainly involved in immune-related pathways, such as Rheumatoid arthritis, NF-kappaB signaling pathway, Osteoclast differentiation, TNF signaling pathway, MAPK signaling pathway, and T-cell receptor signaling pathway." (PMID 36685529, 2022). "Furthermore, it has been observed in autoimmune diseases such as rheumatoid arthritis, where recent studies show a TNFα inhibitor treatment that reduces insulin resistance, delaying the effects on these rheumatoid arthritis patients." (PMID 35455036, 2022). "Adalimumab, a fully human recombinant immunoglobulin G1 (IgG1) anti-TNF monoclonal antibody, was first approved for the treatment of rheumatoid arthritis and subsequently expanded in the treatment of a wide variety of inflammatory conditions such as rheumatoid arthritis and Crohn’s disease." (PMID 36235038, 2022). "Notably, in addition to contributing to cancer development and progression, TNF/TNF-R1-mediated NF-κB signaling has crucial roles in many other autoimmune diseases such as rheumatoid arthritis and Crohn’s disease." (PMID 35222445, 2022). "In line with the immunosuppressive therapy approach, further studies have shown that targeted therapy reduced cardiovascular mortality in rheumatoid arthritis (IL-6, TNF-α, and IL-17A cascades), lupus erythematosus (IL-17A signaling) (Crispín and Tsokos, 2010), and psoriasis (IL-17/IL-23)." (PMID 36267276, 2022). "Etanercept and infliximab, inhibitors of proinflammatory cytokine tumor necrosis factor alpha (anti-TNF), were the first anti-TNF biological drugs indicated for rheumatoid arthritis, and later more biological drugs against TNFα were developed, including adalimumab, certulizumab pegol and golimumab." (PMID 36009355, 2022).
rheumatoid arthritis (continued). "Studies have been shown that PLEK is significantly over-expressed in periodontitis, cardiovascular disease, rheumatoid arthritis, and ulcerative colitis, and thought to be a crucial mediator in the secretion and activation pathways of pro-inflammatory cytokines TNF-α and IL-1β." (PMID 36258174, 2022). "Gastrodia elata Blume (GE) is a traditional Chinese herbal medicine with anti-inflammatory activity, and according to a study, GE significantly decreased the IL-6, CXCL8, MMP-3 and MMP-13 levels in TNF-induced rheumatoid arthritis fibroblast-like synoviocytes (RA-FLSs)." (PMID 36439173, 2022). "A study to determine the association between TNF inhibitors and risk of ASCVD in patients with rheumatoid arthritis, which included 2,101 patients with rheumatoid arthritis in a retrospective cohort study, showed a reduced risk of CHD in patients using TNF-α inhibitors and methotrexate." (PMID 36703734, 2022). "Therefore, TNF inhibitory approaches successfully entered the clinic for therapy of e.g. rheumatoid arthritis (RA), psoriasis, and inflammatory bowel disease (IBD)." (PMID 35122118, 2022). "Additionally, it was shown in synovium of rheumatoid arthritis patients that TNF-α stimulates attraction of DCs and IL-17A secreting T cells." (PMID 35203534, 2022). "In addition, NR4A2 is also up-regulated by the upstream molecule TNFα in synovial tissue, contributing to cartilage destruction and ultimately rheumatoid arthritis." (PMID 36093144, 2022). "In conclusion, we developed a high-affinity, fully human anti-TNFα antibody with low immunogenicity that could potentially have significant therapeutic applications in rheumatoid arthritis or other autoimmune diseases." (PMID 34886761, 2021). "Tumor necrosis factor-alpha (TNF-α) inhibitors indicated in the management of psoriasis, rheumatoid arthritis, ulcerative colitis, Crohn's disease, and other autoimmune diseases have been associated with the development of mycobacterial and other opportunistic infections." (PMID 34812325, 2021). "In the present study, we examined whether serum EV miRNA profiles could be used to distinguish rheumatoid arthritis from ankylosing spondylitis, as well as to predict outcome of TNF inhibitor treatment in both of these rheumatic diseases." (PMID 34691284, 2021). "Inhibition of class I/II HDACs or class III HDACs (Sirtuin) potently influences the activation of macrophages derived from the inflamed joints of patients with rheumatoid arthritis by inhibiting the production of proinflammatory factors, such as IL-6 and TNF-α, and inducing macrophage apoptosis." (PMID 34512154, 2021). "Moreover, vagus nerve stimulation has been used in patients with epilepsy and rheumatoid arthritis, leading to reduced TNF production and attenuated disease severity." (PMID 34572339, 2021). "TNF is also known to be a major regulator of the production of proinflammatory cytokines and has been considered as a therapeutic target for the treatment of some inflammatory diseases such as rheumatoid arthritis and inflammatory disease." (PMID 34733317, 2021). "However, SNX10 knockout in mice reduces the serum levels of TNF-α and IL-1β, resulting in the suppression of immune inflammation and bone erosion in rheumatoid arthritis." (PMID 33594863, 2021). "In our analysis, the top five enriched pathways were rheumatoid arthritis, pertussis, TNF signaling pathway, IL-17 pathway, and NOD-like receptor signaling pathway, which is consistent with the observation the NOD2-related pathways were involved in the pathogenesis mechanism underlying IBD." (PMID 34211502, 2021). "We isolated and screened B cells secreting anti-TNFα antibody from rheumatoid arthritis patients." (PMID 34886761, 2021). "In addition, recent reports include the improvement of insulin resistance and that pancreatic beta cells have beneficial effects on the anti-TNF therapy in rheumatoid arthritis, which supports its potential for improvement cardiovascular risk." (PMID 34830503, 2021).
rheumatoid arthritis (continued). "Finally, the anti-rheumatoid arthritis effects of the four target compounds were validated with the decreased levels of NO, TNF-α, IL-6 and IL-1β in RAW 264.7 macrophage cells treated with LPS." (PMID 34526896, 2021). "TNF-α is equally expressed in the synovial tissue of psoriatic arthritis and rheumatoid arthritis." (PMID 34829740, 2021). "It has also recently been successfully evaluated in rheumatoid arthritis (RA), in patients who had failed multiple lines of anti-TNF biotherapy, with a very good tolerance and a sustained decrease of disease activity equivalent to what is observed with the most effective pharmacological treatments." (PMID 34276328, 2021). "In addition, members of the miR-17–92 cluster were upregulated in CD4+ T cells from patients with systemic lupus erythematosus (SLE), and miR-17 affects TNF-α signaling in rheumatoid arthritis." (PMID 34039371, 2021). "The risk of NMSC and melanoma associated to TNF-α antagonists, such as etanercept, infliximab, and adalimumab has been largely studied in patients with rheumatoid arthritis and Crohn’s disease, and is not established in patients with psoriasis." (PMID 34685480, 2021). "MMP3 is involved in the IL-17 signaling pathway, TNF signaling pathway, and rheumatoid arthritis." (PMID 34830910, 2021). "Additionally, other inflammatory cytokines, such as interleukin (IL)-1, IL-6, and tumor necrosis factor (TNF)-α, are implicated in osteoclast formation in periodontal diseases, postmenopausal osteoporosis, and rheumatoid arthritis." (PMID 33922596, 2021). "Monoclonal antibodies inhibiting cytokines (also referred to as biologic therapy or biologicals) and specifically anti-tumor necrosis factor (TNF)-α have first proved efficacy in the early 90s in the treatment of patients with methotrexate-resistant rheumatoid arthritis." (PMID 33770265, 2021). "This has been reported for several chronicinflammatory diseases, such as cirrhosis, rheumatoid arthritis, andcancer.33−35 Cytokines, such as IL-6 and TNFα, were reportedto increase with cirrhosis progression which supports the link todownregulation of expression." (PMID 34428046, 2021). "Interestingly, even when the autoimmune disease is primarily tumor necrosis factor (TNF)/IL-6 driven (as in rheumatoid arthritis), blocking IL-1β signaling reduced disease severity." (PMID 33643264, 2021). "Among the deregulated pathways, the top 5 downregulated KEGG pathways were as follows: cytokine-cytokine receptor interaction (ko04060), IL-17 signaling pathway (ko04657), NOD-like receptor signaling pathway (ko04621), TNF signaling pathway (ko04668), and rheumatoid arthritis (ko05323)." (PMID 34535196, 2021). "This is consistent with observations following aHSCT in refractory Crohn’s Disease and use of anti-TNFα therapy after aHSCT and in rheumatoid arthritis and use of disease-modifying agents after aHSCT, where there is renewed sensitivity to drugs associated with the “immune reset” after aHSCT." (PMID 34025648, 2021). "These DEGs were enriched in cytokine–cytokine receptor interaction, legionellosis, chemokine signaling pathway, amoebiasis, TNF signaling pathway, salmonella infection, hematopoietic cell lineage, rheumatoid arthritis, pertussis, and staphylococcus aureus infection." (PMID 34193119, 2021). "For example, in rheumatoid arthritis BiP at the cell surface can stimulate tumor necrosis factor (TNF) production to promote inflammation, but BiP can also act as an antigen to stimulate CD8-positive T cells leading to increased production of the anti-inflammatory cytokine IL-10." (PMID 34268295, 2021). "Interestingly, anti-TNF-α therapy is currently used for inflammatory diseases as rheumatoid arthritis, and other pathologies." (PMID 34172716, 2021). "Interestingly, while Dnase2a-Tmem173 (gene encoding STING) double KO mice were healthy Dnase2a-Ifnar1 double-KO mice develop rheumatoid arthritis that was driven by TNFα (Tumor Necrosis Factor-α)." (PMID 33717156, 2021).